CD44 (CD44 molecule (IN blood group))
Diseases named in the same sentence as CD44 in open-access papers (continued):
Sharing a sentence is not in itself a finding about the gene and the disease.
tumor (continued). "Recently, miR-143 was shown to inhibit tumor progression of BC metastatic cells, both in vivo and in vitro, by directly targeting CD44." (PMID 32731349, 2020). "Meanwhile, HA is employed to achieve active tumor targeting by recognizing CD44 overexpressed on the surface of tumor cell membranes." (PMID 32328426, 2020). "The up-regulation of CD44 observed in KIR2DL2/L3/S2+ CD8+ T cells will favor their interaction with VLA-4 integrin in order to facilitate their infiltration in the tumor and their contact with dendritic and other immune cells." (PMID 33076479, 2020). "The expression of a subset of genes is associated with CSCs, including markers such as Lgr5, CD133, and CD44, as well as other genes involved in the acquisition of stemness traits in tumor cells, such as transcription factors Nanog, Stat‐3, and c‐Myc." (PMID 31788944, 2020). "N‐linked glycosylation was found earlier to positively correlate with binding of CD44 to HA in lung epithelium‐derived tumor cells expressing CD44s which include the A549 cells used in this study." (PMID 32592613, 2020). "It has been demonstrated that, from an oncological point of view, CD44 has a considerable importance in the study of progression and tumor invasiveness." (PMID 32349323, 2020). "CD44 represents another reliable marker: indeed, CD44+ GSCs present high tumor-sphere forming and tumorigenic potential, and have the capability to restore the heterogeneity of the parental GBM." (PMID 32391266, 2020). "Al-Hajj and colleagues were the first to identify tumor-initiating CSCs in BC by using cell surface markers CD44 and CD24." (PMID 33327542, 2020). "The treatment efficacy of CD44-targeted NIR-PIT combined with anti-PD-1 mAb therapy was examined in vivo in a subcutaneously allografted MOC2-luc tumor model." (PMID 33322807, 2020). "Some scholars insist that tumor stem cells can resist to chemotherapy, and that a higher expression of CD44+/CD24- tumors displayed greater resistance to neoadjuvant chemotherapy." (PMID 33584277, 2020). "For example, the expression of tumour suppressor miRNA-34a is usually relatively low in various cancers, such as PC, NSCLC, and ALL, and it has been identified as a tumour suppressor with multiple targets, including CD44, PD-L1, ZEB1, and BCL-2." (PMID 32340605, 2020). "One of the targets of the hsa-miR-142-5p isoforms is CD44, which is a tumor stem cell marker and receptor for hyaluronan, collagens, and matrix metalloproteinases in various tissues acting also as a cofactor for VEGF and FGF2 binding." (PMID 32566253, 2020). "As performed previously, we decided to assess the tumor sphere formation ability of CD44+/EPCAM+ cells." (PMID 32391123, 2020). "CD44 has multiple functions, including lymphocyte activation, recirculation, homing, haematopoiesis and tumour metastasis." (PMID 32414170, 2020). "CD44 is also expressed on activated immune cells in tumor beds as well as cancer stem cells or immunosuppressive cells." (PMID 32937841, 2020). "Other markers that showed differential expression in specific tumor groups included CD44, EMA, and β-catenin." (PMID 31252633, 2019). "The adhesion molecule CD44 was reported to be highly expressed on different tumor cells and to suppress T cell-mediated immune responses." (PMID 31555275, 2019). "Their findings revealed that expression of CD44+ a lineage marker was indispensable for persistent tumor heterogeneity in HNSCCs." (PMID 31030466, 2019). "So far, at least 15 different CD44-regulating miRs have been identified mainly exhibiting tumor suppressive activities by exerting anti-proliferative, anti-invasive, anti-angiogenic and apoptosis-promoting functions." (PMID 31741714, 2019). "In general, enrichment of the cell surface glycoprotein CD44 in tumor cells including breast is correlated with invasive and metastatic characteristics of the cancer and hence poor prognosis." (PMID 31361756, 2019).
tumor (continued). "In contrast, higher expression of CD44 on the tumor cells and increased PD-1 expression in the peripheral blood of patients was correlated with poor tumor differentiation and the aggressiveness of the tumors." (PMID 31878338, 2019). "Alterations in splice site usage or selection have been shown to affect genes implicated in cancer susceptibility (BRCA1) and in tumor development or progression (e.g., MDM2, CD44)." (PMID 31683936, 2019). "As in previous studies, we observed that miR-34a overexpression in UC cells inhibited tumor invasion and reduced drug resistance, probably through the inhibition of CD44." (PMID 31569404, 2019). "Our results suggest that CD44 has a significant effect on the HA content on the surface and between tumor cells, regulating the composition of tumor microenvironment." (PMID 30909497, 2019). "miR-302a overexpression or CD44 knockdown reduced the number and diameter of tumor spheres and decreased stem cell marker expression." (PMID 31754405, 2019). "Emerging literature reveals the association of CD44 with MMP-9 in mouse and human tumor cells to enhance the invasion of cancer cells." (PMID 31579438, 2019). "Remarkably, in breast tumor specimens, tumor cells that express both CD90 and CD44 are confined to the periphery of the tumor, representing the tumor invasive front." (PMID 31080802, 2019). "In CD44-positive tumors, HA staining was intense around and between tumor cells, colocalizing with the plasma membrane CD44 signal." (PMID 30909497, 2019). "Flow cytometry assay revealed CD133 and CD44 enriched cells in distal margin and tumour compared to normal colorectal tissues, which was further confirmed by immunohistochemistry." (PMID 30950180, 2019). "CD44 has been suggested as a target for immunotherapy or as a treatment, using antibodies conjugated to anti-tumour agents." (PMID 31450747, 2019). "Overall, our results showed that despite of the relatively low HA secretion levels of MKN74 tumor cells, CD44 has a significant effect on the HA content, regulating the pericellular HA assembly on the surface and between tumor cells." (PMID 30909497, 2019). "CD44 is a hyaluronic acid receptor and has been found to participate in diverse cellular processes, such as tumor metastasis, cell migration, proliferation." (PMID 30996686, 2019). "Ninety-three (41%) patients had cytokeratin-positive tumor cells in either blood or bone marrow, while cells expressing CD44 were found in 22 (10%) cases." (PMID 30056567, 2019). "We also found that CD44 was upregulated in stem cell-enriched tumor spheres, and miR-302a overexpression or CD44 silencing showed consistent inhibitory effects on tumor sphere growth and the expression of stem cell markers." (PMID 31754405, 2019). "We also provide evidence for the first time that HCC CTCs contain CD44+ cancer stem cell populations and CTM which were associated with tumor stage." (PMID 31819089, 2019). "During HA/CD44 signaling, miR-21 has also been suggested to regulate tumor cell proliferation, invasion, survival, chemoresistance and tumor progression." (PMID 31293964, 2019). "The tumor tissue derived from miPS-Huh7cm cells was found to be rich in CSCs expressing CD44, liver CSC marker, CK19 and interphase marker Ki67, as well as GFP, indicating the presence of miPSHuh7cm-derived cells." (PMID 31450740, 2019). "Cancer cells often express a variety of CD44 isoforms, which enables the regulation of multiple oncogenic pathways required for cancer progression and tumour development." (PMID 30857150, 2019). "Tumor initiating cells (TIC) usually display some of the properties of tissue stem cells, express surface markers such as CD44 and Sca-1 characteristic of such cells, and appear to play key roles in tumor initiation and metastasis." (PMID 31514477, 2019). "Post-doxycycline tumor samples demonstrated a statistically significant 40% decrease in the stemness marker CD44, when compared to pre-Doxycycline tumor samples." (PMID 31002656, 2019).
tumor (continued). "Abnormal expression of CD44 significantly enhances tumor cell migration, which is closely related to tumor metastasis." (PMID 31832018, 2019). "In contrast, CD39 was significantly overexpressed only by CT26.WT-NFs and at the same level as found in NFs from healthy mice, while CD44 was significantly underrepresented in NFs from tumor mice and healthy mice in comparison to CAFs." (PMID 31428583, 2019). "Regarding tumor formation, cells with high expression of CD44 showed the dominance in tumor sizes and weights." (PMID 31049070, 2019). "Downregulation of Vimentin and CD44 in response to NS1643 was also observed in tumor xenografts derived from ER-negative cell lines." (PMID 30792401, 2019). "Post-treatment CD44 staining intensity was positively correlated with baseline SUVmax and negatively correlated with change in tumor size." (PMID 30999901, 2019). "The percent of post-treatment CD44-positive cells was positively correlated with baseline SUVmax and post-treatment SUVmax; and negatively correlated with tumor size." (PMID 30999901, 2019). "Intriguingly, a CD26+ circulating tumor cell (CTC) population that is CD44+ and CD66c+ but EpCAM− and CD133− is an independent prognostic factor for CRC recurrence." (PMID 31285270, 2019). "CD44 is expressed at low levels in normal tissues; however, it is pathologically and highly expressed on the surface of tumor cells." (PMID 31920642, 2019). "In pancreatic cancer, asporin was also shown to interact directly with CD44 in co-precipitation assays, and asporin not only facilitated cancer cell migration and invasion in vitro but also enhanced tumor metastasis in vivo." (PMID 31608236, 2019). "CD44, a major cell adhesion receptor of HA, is abundantly found (relative to normal cells) in the tumor extracellular matrix." (PMID 31266194, 2019). "Yet, CD44 is involved in tumor progression, metastasis, drug resistance and its expression has been correlated to disease prognosis." (PMID 35582577, 2019). "Nevertheless, our results support a strategy that can be applied to a large number of “dirty” targets in which target expression is present at high density on tumor tissue, yet still quite significant on normal host tissue, such as CD44." (PMID 31891584, 2019). "Sphere-formation and subcutaneous transplantation assays indicated that CD44+/CD133+ cells were characterized by increased self-renewal in vitro and tumor-propagating capacity in vivo when compared with CD44−/CD133− cells." (PMID 30804456, 2019). "We found that the number and diameter of tumour spheres formed per 100 cells and the proportion of CD44+CD24− phenotype cells were significantly reduced in SKBR3‐S but not MCF‐7‐S cells after stable transfection of a lentiviral vector encoding miR‐200c." (PMID 31599500, 2019). "IHC of xenograft tumor samples confirmed that human CD44 protein was nearly undetectable in co-grafts with MDA-MB-468 shCD44 855 (shScramble vs. shCD44 855)." (PMID 31762938, 2019). "We found that the BCSCs had the ability form tumor spheres, and CD44 significantly increased in tumor spheres using a high-content system immunofluorescence." (PMID 31612865, 2019). "G‐MDSCs and M‐MDSCs promoted tumor sphere formation and increased the CD44+ and CD133+ cell percentages." (PMID 31559140, 2019). "The total HA staining coverage of tumor sections was analyzed, and there was a significant increase in the intensity of HA staining in CD44-positive tumors as compared to MOCK tumors, which is in line with the results of the cell cultures." (PMID 30909497, 2019). "Not only did more tumor infiltrating CD8+ T-cells in LL-37DC treated tumors express the activation markers CD44 and PD1, but we also observed an increase in the expression level of PD1 on these CD8+ T-cells." (PMID 31413918, 2019). "Consistent with the in vitro findings, EMT marker upregulation, RhoA downregulation, CD44 overexpression, and tumor phenotypes of ccRCC were observed in mice with chronic exposure to 3MC." (PMID 30872677, 2019).
tumor (continued). "Accordingly, we examined the correlations of tumor burden, the induction of CD44+ cells, and CSC-like properties, in the context of the complex interplay between the primary tumor, the microenvironment, and the transition to more aggressive disease." (PMID 31315262, 2019). "We therefore analyzed the expression of a number of adhesion-associated proteins (E-selectin, N-cadherin, ICAM-1, VCAM-1; CD44, integrin α4, integrin α5, integrin β1) in tumor cells and endothelial cells using Western blot." (PMID 30717801, 2019). "In fact, it has been seen that the interaction between versican and CD44 affects the proliferation and motility of tumor cells." (PMID 31534630, 2019). "CD44 is involved in cell-cell and cell-matrix adhesion and acts as cancer stem cell and prognostic marker in several tumor entities." (PMID 31661833, 2019). "Here all tumor-infiltrating CD4+ or CD8+ T cells were CD44+, indicating that they were activated or possibly antigen-experienced." (PMID 31601678, 2019). "Due to the fact of high CD44 expression levels in various tumor diseases, anti-CD44 antibodies are currently under investigation as potential anti-tumoral immune therapeutics in different animal studies to reduce tumor progression." (PMID 31741714, 2019). "Within the hypoxic tumor areas CD44 gene expression is induced via hypoxia-inducible factor (HIF)-1α." (PMID 31052565, 2019). "CD44 has been reported to be involved in the regulation of cell growth, survival, differentiation, motility, tumor growth, proliferation, and metastasis." (PMID 30788285, 2019). "The lowest levels of co-expression (40%) were found in the grade 2 tumor that also had the lowest content in CD44+ cells." (PMID 31627418, 2019). "Put together, histopathology analysis showed lack of neoplastic characteristics in normal and distal tissues but immunohistochemistry showed enriched expression of CD133 and CD44 in epithelial cells of tumour as well as distal tissues." (PMID 30950180, 2019). "CD44 expression increased in tumor cells after chemotherapy in 7 cases, was unchanged in 15 cases, and decreased in 2 cases of the 24 evaluable paired cases." (PMID 30999901, 2019). "The protein CD44 bound with hyaluronic acid and sugar rich coating molecules is found on the surface of endothelial cells and tumour cells." (PMID 31345216, 2019). "Immunoreactivity to CD44, E-cadherin and N-cadherin implied the heterogeneous phenotypes in malignant tumor derived from miPS-PLCcm cells." (PMID 31426391, 2019). "The common markers of CSCs are CD34+CD38− for AML, and CD133+, CD44+, and others for solid tumors, as these cells display higher abilities of tumor ignition in nude and NOD/SCID mice." (PMID 31336602, 2019). "When compared to non-SS sicca subjects, the two most upregulated of these proteins in pSS patients, FKBP1A and CD44, play a role in adaptive immunity through T-cell activation and proliferation, in addition to promoting tumour growth and progression." (PMID 31366407, 2019). "Alternatively, the HA receptor CD44 is a marker of cancer stem cells and tumor initiating cells in PDAC." (PMID 31490946, 2019). "Hyaluronic acid (HA) is yet another source which shows an affinity with CD44 therefore, HA in conjugation with CD44 can be used as a formulation to avail HA in the tumor-specific site." (PMID 31689930, 2019). "CD8+CD44+CD62L− T cells were specifically sorted because that was the phenotype of most MC38 tumor-infiltrating CD8+ T cells." (PMID 31477729, 2019). "CD44 is known as a ‘homing receptor’, because HA-CD44 interactions mediate the recruitment of activated leucocytes, stem cells and tumor cells from the circulation." (PMID 30909497, 2019). "Compared with SW48-GFP, co-injection of SW48-GFP and CC-CAFs enhance the count of tumor cells adhered to endothelial cells of lung within 48 h significantly and knock down of CD44 can decrease the effect." (PMID 31367190, 2019).
tumor (continued). "CD44 expression level is therefore correlated with tumor grade, lymph node invasion, metastatic spread, and overall prognosis." (PMID 31294922, 2019). "Our results showed that NF1-knockdown tumor had higher percentage of vimentin and CD44-positive cells." (PMID 30967630, 2019). "Put together, these results suggest the involvement of altered Wnt signalling behind the enrichment of CD133 and CD44 in tumour as well as distal tissues." (PMID 30950180, 2019). "In a study of the association of CD44-expressing CAFs and cancer cell stemness, it was shown that stromal CD44 expression was predominantly found in hypoxic areas of tumor tissue." (PMID 31428583, 2019). "It has also been shown that disseminated tumor cells (DTCs) and CTCs express the putative stem cell CD44+/CD24− and/or ALDH1+/CD24− phenotypical profile." (PMID 31261917, 2019). "CUR-loaded CSO-SA micelles reduced the size of tumor and the subpopulation of CD44+/CD24+ cell in nude mice tumor tissue." (PMID 30890933, 2019). "Many efforts have been invested for the development of HA-based micelles, due to the efficient binding of HA to its receptor, CD44, and the release of the drug cargo after internalization into the tumor." (PMID 31060303, 2019). "Our preclinical data revealed a higher percentage of CD44-positive cells in xenografts in the context of a greater tumor burden." (PMID 31315262, 2019). "Immunohistochemical analysis revealed that overexpressing miR-330-3p increased PCNA, cyclin D1, CD44 and β-catenin, and reduced cleaved caspase-3 and Bax in tumor tissues." (PMID 31498117, 2019). "CAM tumor paraffin sections were double-stained with CD44 antibody and HABC to analyze the amount and localization of CD44 and HA." (PMID 30909497, 2019). "CD44 is a transmembrane glycoprotein which has also been identified as being expressed by many tumor CSCs." (PMID 31139149, 2019). "The results showed that the number and diameter of tumour spheres formed and the proportion of CD44+CD24− phenotype cells from SKBR3‐S were noticeably decreased." (PMID 31599500, 2019). "The transmembrane glycoprotein CD44 is constitutively expressed on embryonic stem cells, in connective tissues and in the bone marrow and overexpressed in different tumor entities as well as in cancer stem cells (CSC)." (PMID 31741714, 2019). "Comparison of protein expression between tumor samples and paired normal tissues showed a significantly increased expression of CD44 and GLUT1 in tumor samples (p = 0.004 and p < 0.001)." (PMID 31316469, 2019). "Hyaluronan (HA), one of the major ECM (extracellular matrix) components have been identified as a physiological ligand for surface CD44 isoforms which are frequently overexpressed in malignant tumor cells during cancer progression." (PMID 31293964, 2019). "We characterized the cell surface receptor CD44 as one of the best markers of the enrichment of gastric CSC among the cells composing the tumor mass." (PMID 31010193, 2019). "Numerous studies have shown that CD44, a membrane glycoprotein, is involved in processes of tumor cell migration and invasion." (PMID 31534630, 2019). "To rule out the effect of cell culture, we additionally assessed the expression of SOX2, Vimentin and CD44 protein in NF1-LRD-expressing tumor." (PMID 30967630, 2019). "Different delivery systems combining PTX and HA have been previously evaluated for targeting CD44-overexpressing tumor cells." (PMID 31060303, 2019). "Overexpression of miR‐200c resulted in a significant reduction in the number of tumour spheres formed and the population of CD44+CD24− phenotype mammospheres in SKBR3‐S." (PMID 31599500, 2019). "In a separate experiment, tumor growth of MDA-MB-468 + 3T3HAS3 CD44 KO T1 co-grafts was slightly greater than that of MDA-MB-468 + 3T3HAS3 co-graft tumors (p < 0.05)." (PMID 31762938, 2019). "For example, CD44 can perform tumor-promoting or -suppressing functions depending on its association with protein partners." (PMID 31134064, 2019).